PIM3 (Pim-3 proto-oncogene, serine/threonine kinase)
Diseases named in the same sentence as PIM3 in open-access papers (continued):
Sharing a sentence is not in itself a finding about the gene and the disease.
carcinoids (1 paper, 2020). "The aim of this pilot study was to determine mRNA and protein levels of NEK2, PIM1, and PIM3 in a group of 49 patients with BP-NENs: 11 typical carcinoids, 5 atypical carcinoids, 11 large cell neuroendocrine carcinomas, 22 small cell lung carcinomas (SCLC)." (PMID 32504181, 2020). "Our results reveal abundant PIM3 expression in all BP-NENs, but surprisingly, no higher expression was found in highly aggressive neuroendocrine cancers compared with less aggressive carcinoids." (PMID 32504181, 2020).
cardiac hypertrophy (1 paper, 2025). "Based on these findings, we propose that Pim3 might be involved in DM-associated cardiac hypertrophy and subsequent HF." (PMID 39850120, 2025). "This study aims to investigate whether Pim3 is involved in DM-induced cardiac hypertrophy and HF and to elucidate its underlying mechanisms." (PMID 39850120, 2025). "Hyperglycemia induced nuclear translocation of YY1, leading to Pim3 up-regulation, eventually developing into cardiac hypertrophy and HF." (PMID 39850120, 2025). "Taken together, these data indicate that Pim3 is involved in hyperglycemia-induced cardiac hypertrophy and HF." (PMID 39850120, 2025). "Pim3 knockdown markedly reduced the hyperglycemia-induced mRNA and protein expression of cardiac hypertrophy markers (atrial natriuretic peptide [ANP] and β-myosin heavy chain [MHC]), attenuated cardiac hypertrophy, and improved cardiac dysfunction." (PMID 39850120, 2025). "Under hyperglycemic conditions, sustained YY1 nuclear translocation induced significant Pim3 up-regulation, eventually leading to cardiac hypertrophy and HF in mice." (PMID 39850120, 2025). "Theoretically, Pim3, which has a similar structure to Pim1, should play a central role in the pathogenesis of DM-induced myocardial hypertrophy and HF." (PMID 39850120, 2025). "Our data suggest that targeting Pim3 may be effective for treating DM-induced myocardial hypertrophy and HF." (PMID 39850120, 2025). "In this study, we demonstrated that hyperglycemia-induced sustained YY1 nuclear translocation strengthened the binding of YY1 to the Pim3 promoter and markedly enhanced Pim3 promoter transcription activity, leading to Pim3 up-regulation, eventually contributing to cardiac hypertrophy and HF." (PMID 39850120, 2025). "Pim3 knockdown markedly attenuated myocardial hypertrophy and cardiac dysfunction." (PMID 39850120, 2025). "However, whether proviral insertion of Moloney virus 3 kinase (Pim3), a proto-oncogene, contributes to cardiac hypertrophy in diabetes mellitus (DM) remains unknown." (PMID 39850120, 2025). "Indeed, as we expected, YY1 was involved in hyperglycemia-induced Pim3 up-regulation in cardiomyocytes by binding to the Pim3 promoter and markedly enhancing Pim3 promoter transcription activity, eventually contributing to cardiac hypertrophy and HF." (PMID 39850120, 2025). "Pim3 or YY1 knockdown profoundly reduced cell size and inhibited the mRNA and protein expression of cardiac hypertrophy markers, as well as markedly attenuating myocardial hypertrophy and cardiac dysfunction." (PMID 39850120, 2025).
chronic obstructive pulmonary disease (1 paper, 2024). A chronic and progressive lung disorder characterized by the loss of elasticity of the bronchial tree and the air sacs, destruction of the air sacs wall, thickening of the bronchial wall, and mucous accumulation in the bronchial tree. "Similarly, another study on chronic obstructive pulmonary disease (COPD) showed that the mRNA and protein levels of PIM3 were upregulated in COPD tissue as compared to normal lung tissue, which was also verified using animal experiments." (PMID 39092429, 2024).
Ewing sarcoma (1 paper, 2011). A small round cell tumor that lacks morphologic, immunohistochemical, and electron microscopic evidence of neuroectodermal differentiation. "Significantly less is known about how Pim-3 expression is regulated, albeit one report shows that Pim-3 can be regulated by the Ets family of transcription factors in NIH 3T3 and human Ewing’s sarcoma cells." (PMID 21646687, 2011).
Fulminant hepatic failure (1 paper, 2013). Hepatic failure refers to the inability of the liver to perform its normal synthetic and metabolic functions, which can result in coagulopathy and alteration in the mental status of a previously healthy individual. "The pim-3 gene also protected rats from fulminant hepatic failure by inhibiting liver apoptosis and improving the inflammatory response of liver tissues, which was associated with inhibiting the expression of inflammatory mediators and promoting the production of the anti-apoptosis protein Bcl-2." (PMID 23825534, 2013).
Hyperglycemia (1 paper, 2025). An increased concentration of glucose in the blood. "Yin Yang 1 (YY1), which translocated from the cytoplasm into the nucleus under hyperglycemia, bound to the Pim3 promoter and enhanced Pim3 transcriptional activity." (PMID 39850120, 2025). "Collectively, YY1 mediated hyperglycemia-induced Pim3 expression, both in HG-treated H9C2 cells and in streptozotocin-induced diabetic hearts." (PMID 39850120, 2025). "This showed that hyperglycemia increased Pim3 expression at the RNA level." (PMID 39850120, 2025). "Thus, we proposed that hyperglycemia might be involved in the transcriptional regulation of Pim3 by targeting transcription factors." (PMID 39850120, 2025). "However, treatment with Pim3 siRNA, but not scrambled siRNA, significantly attenuated hyperglycemia-induced effects (P<0.05)." (PMID 39850120, 2025). "Furthermore, the mRNA and protein expression of Pim3 was significantly up-regulated when H9C2 cells were exposed to HG compared with the control group (P<0.05), while treatment with YY1 siRNA, but not scrambled siRNA, markedly attenuated these hyperglycemia-induced effects (P<0.05)." (PMID 39850120, 2025).
kidney damage (1 paper, 2023). "Pim3 is a kind of aldosterone regulatory protein with the ability to promote the expression of aldosterone, and the abnormal increase of aldosterone can increase the blood pressure of patients, which can result in the occurrence of heart, liver, and kidney damage in severe cases." (PMID 37592331, 2023).
Lewis lung carcinoma (1 paper, 2024). "Moreover, conditioned media from B16-F10, 4T1 or Lewis lung carcinoma (LLC) cultures similarly induced PIM3, INHBB and BCL3 expression, indicating that secreted factors of multiple cancer cell types induced rCap marker expression in cultured ECs." (PMID 39627185, 2024).
neuroendocrine tumors (1 paper, 2020). "In addition, the fact that PIM3 expression is abundant in all lung neuroendocrine tumors, which was revealed in our research, suggests that this kinase could be potentially a target also in the treatment of other BP-NEN entities." (PMID 32504181, 2020).
pheochromocytoma (1 paper, 2024). "PIM3 was originally known as a kinase induced by depolarization (KID-1) in rat pheochromocytoma cells, but it was later renamed PIM3 because of its sequence similarity with other PIM family proteins." (PMID 38339286, 2024).
rectal cancer (1 paper, 2017). A primary or metastatic malignant neoplasm that affects the rectum. "In conclusion, this study showed that Pim-3 expression in rectal cancer was associated with poor response to chemoradiotherapy and poor prognosis." (PMID 29167471, 2017). "We hypothesized that Pim-3 expression in rectal cancer tissue may be associated with chemotherapy resistance; however, no prior studies have reported on the relationship between response to chemoradiotherapy and Pim-3 expression in rectal cancer." (PMID 29167471, 2017). "Our result confirmed that Pim-3 expression (RR = 4.47, 95% CI: 1.94–10.018; P = 0.001) in rectal cancer tissue played key roles in chemoradiotherapy resistance." (PMID 29167471, 2017). "These are the possible reasons for the aggressive biological behaviors and poor prognosis of rectal cancer patients with high Pim-3 expression." (PMID 29167471, 2017). "In the present study, Pim-3 expression, along with the number of neoadjuvant chemotherapy cycles, was demonstrated to be a predictor of prognosis in rectal cancer patients after at least 39 months of follow-up." (PMID 29167471, 2017). "The relationship between Pim-3 expression on immunohistochemical analysis of rectal cancer tissue, which was obtained before treatment, the response to chemoradiotherapy and survival was investigated." (PMID 29167471, 2017). "Pim-3 is a potential predictive biomarker for the response of rectal cancer to chemoradiotherapy." (PMID 29167471, 2017). "Therefore, the relationship between Pim-3 expression and response to neoadjuvant chemoradiotherapy in rectal cancer patients is important to evaluate." (PMID 29167471, 2017). "Pim-3 is a potential predictive maker of the response to chemoradiotherapy in rectal cancer." (PMID 29167471, 2017). "Our previous study showed Pim-3 is expressed differently in rectal cancer tissues and that it could be an important contributor to chemoradiotherapy resistance." (PMID 29167471, 2017). "Therefore, the present study aimed to detect Pim-3 expression in rectal cancer and the response to chemoradiotherapy in such cases." (PMID 29167471, 2017). "Locally advanced rectal cancer patients with negative Pim-3 expression were more likely to achieve a better chemoradiotherapy response." (PMID 29167471, 2017). "This study enrolled 175 patients with pathologically confirmed rectal cancer who received neoadjuvant chemoradiotherapy; of these, 130 patients demonstrated Pim-3 expression in the primary tumor, while 45 patients were negative for Pim-3 expression." (PMID 29167471, 2017).
Sézary Syndrome (1 paper, 2014). "Furthermore, PIM1 and, again, especially PIM2, but not PIM3 expression was increased in a panel of 8 PTCL cell lines and primary tumoral T cells from 5 Sézary Syndrome patients relative to normal T cells from 3 healthy donors." (PMID 25386922, 2014).
Shock (1 paper, 2025). The state in which profound and widespread reduction of effective tissue perfusion leads first to reversible, and then if prolonged, to irreversible cellular injury. "In summary, this study revealed the critical involvement of the IL-6/JAK/STAT3, PI3K/Akt/mTOR, and TNF-α/NF-κB pathways in pediatric postoperative septic shock and identified key genes such as PIM3, with quercetin and astramembrannin I predicted as potential therapeutic compounds." (PMID 41189212, 2025).
T-cell leukemia (1 paper, 2014). A malignant disease of the T-lymphocytes in the bone marrow, thymus, and/or blood. "FACS analysis of four PIM1/MYC mice and one mouse from PIM2, PIM3, and BCLxl cohorts demonstrates only myeloid cell (GR-1 and CD11b) markers, indicating a myeloid, not T-cell leukemia." (PMID 25238262, 2014).
T-cell lymphomas (1 paper, 2014). "Pim1 was discovered as a proviral insertion site in Moloney-murine leukemia virus in T-cell lymphomas, and further studies identified the other two family members, pim2 and pim3, as alternative integration sites." (PMID 24860787, 2014).
tumor (42 papers, 2011 to 2026). "Upregulation of PIM3 is associated with poor patient prognosis, and its inhibition leads to reduced cell proliferation, invasion, and in vivo tumor growth; thus, PIM3 represents an emerging novel therapeutic target in cancer." (PMID 38339286, 2024). "Emerging evidence has shown that the PIM serine/threonine kinase family, including PIM1, PIM2 and PIM3, is associated with tumour progression towards metastasis." (PMID 29472550, 2018). "PIM3 expression is suppressed in cells with loss of the tuberous sclerosis complex (TSC) tumor suppressors, which exhibit growth factor-independent activation of mTORC1, and in the mouse liver upon feeding-induced activation of mTORC1." (PMID 29170467, 2017). "Notably, PIM1 and PIM3 were frequently upregulated in GC tumor tissues and have been associated with poor prognosis and increased tumor aggressiveness." (PMID 40992658, 2025). "The antitumor efficacy of shRNA may be mainly dependent on the apoptosis of tumor cells caused by silencing of Pim-3." (PMID 31849942, 2019). "The expression level of PIM3 can be validated by RNA-seq, and it is found that tumor samples with exon 6 deletion revealed a lower expression level." (PMID 40623120, 2025). "Next, we established a subcutaneous tumor model in C-NKG mice using 1806 cells to examine the anti-tumor efficacy of PIM3 KO CAR-T cells in vivo." (PMID 41199316, 2025). "Immunohistochemical staining results exhibited increased PIM3 KO CAR-T cells in tumor tissues, which contributed to better tumor-eliminating rate in mice." (PMID 41199316, 2025). "In this hypoxic model, PIM3 KO CAR-T cells exhibited better long-term tumor-killing capacity as expected." (PMID 41199316, 2025). "Inhibition of PIM3 can promote tumor cell death and prevent angiogenesis, leading to a dual effect on tumor growth." (PMID 38339286, 2024). "PIM3 also inhibits p27 expression at the transcriptional and post-translational stages to promote cell cycle progression, proliferation, and tumor growth." (PMID 38339286, 2024). "The JAK-STAT pathway is known to regulate metastasis and tumor angiogenesis, and interestingly, two prominent rCap markers Pim3 and Bcl3 are direct transcriptional targets of the JAK-STAT pathway." (PMID 39627185, 2024). "PIM3 was found to be expressed in a variety of human Ewing’s family tumor cell lines and forced PIM3 expression using a retroviral vector, increasing anchorage-independent growth." (PMID 38339286, 2024). "Genetic inhibition of PIM3 expression suppresses in vitro cell proliferation and in vivo tumor growth and metastasis in mice with solid cancers, indicating that PIM3 is a potential therapeutic target." (PMID 38339286, 2024). "The co-expression of PIM3 (+), c-Myc (+), and p-p27 (+) was closely correlated with poor differentiation, advanced tumor stage, and lymph node metastasis." (PMID 38339286, 2024). "Overall, owing to its contribution to oncogenic signaling, PIM3 is a viable molecular target that suppresses cancer cell proliferation, survival, invasion, tumor growth, metastasis, and progression." (PMID 38339286, 2024). "Recent studies indicate that PIM3 plays a pivotal role in cancer proliferation, survival, invasion, metastasis, angiogenesis, tumor growth and progression, chemo/radiation resistance, and the immunosuppressive microenvironment." (PMID 38339286, 2024). "PIM3 is highly expressed in tumor tissues, particularly in those derived from the endoderm, such as the liver, pancreas, colon, and stomach." (PMID 38339286, 2024). "Meanwhile, Mono-FCGR3A both in high and low tumor infiltration group expressed high level of PIM2/PIM3 compared to HDs." (PMID 36532059, 2022). "In that study, higher PIM3 expression correlated with significantly worse patient survival independent of histologic subtype, alpha-fetoprotein levels, or tumor stage." (PMID 35892829, 2022).
tumor (continued). "Mice injected with PIM3 knockout cells had decreased tumor volumes and their tumors demonstrated decreased Ki67 staining, denoting decreased proliferation, compared to animals bearing tumors from wild-type cells." (PMID 35892829, 2022). "Further, Western blotting results showed that the expression of Pim-3 in tumor tissues was significantly reduced after shRNA and dual-function vector therapy." (PMID 31849942, 2019). "Inhibition of Pim-3 kinase or silencing of Pim-3 inhibits tumor growth and enhances apoptosis of tumor cells." (PMID 31849942, 2019). "Next, we examined the changes of TLR7 activation and Pim-3-silencing-related apoptosis of tumor tissues after different treatment." (PMID 31849942, 2019). "Immunohistochemical (IHC) staining for PIM3 in the parent and COA67 PDX tumor showed that PIM3 was present in both the human parent tumor from which COA67 was derived and a COA67 PDX tumor specimen harvested from a mouse." (PMID 29854306, 2018). "The potential mechanisms by which PIM-3 promotes tumours include upregulation of pSTAT3Try705, pSurvivinThr34 and VEGF, activation of the AKT/β-catenin pathway, phosphorylation of Bad, and inhibition of Bcl-xl." (PMID 27596051, 2016). "DHPCC-9 treatment significantly decreased the volume of Pim-3-overexpressing tumors, suggesting that this compound had been able to reach the tumor tissue and inhibit Pim-3 activity there." (PMID 26075720, 2015). "Furthermore, we conducted the tumor spheroid killing assay, which used a three-dimensional model to mimic tumor hypoxia, and observed a much higher spheroid killing efficiency in the PIM3 KO group." (PMID 41199316, 2025). "PIM3 plays a critical role in activating multiple oncogenic signaling pathways promoting cancer cell proliferation, survival, invasion, tumor growth, metastasis, and progression, as well as chemo- and radiation therapy resistance and immunosuppressive microenvironment." (PMID 38339286, 2024). "Interestingly, Pim3, Bcl3 and Inhbb were upregulated in ECs isolated from the lungs and liver 14 d after tumor cell inoculation, a time point where CTCs were present, as indicated by the liver metastases." (PMID 39627185, 2024). "Bufothionine therapy also reduced the expression of PIM3 in xenograft tumor tissues." (PMID 38339286, 2024). "Immunohistochemistry (IHC) and immunoblot analysis of tumor lysates confirmed elevated PIM3 levels and more effective inhibition of pPRAS40, pS6, p4EBP1, pBAD by the combination treatment in the G-R3 X1.2 tumors, while ipatasertib alone was effective in the Par X1.6 tumors." (PMID 35440108, 2022). "Similar to the G-R cells established in vitro, elevated levels of PIM3 protein were also observed in the R0068 X1.2 tumor lysates compared to Par X1.6 tumors and enhanced inhibition of tumor growth and downstream markers was observed when ipatasertib was combined with GDC-0339 in vivo." (PMID 35440108, 2022). "For example, niraparib and rucaparib have also been found to inhibit some kinases including DYRK15, CDK16 and PIM3 that may be therapeutically useful if these kinases are aberrantly expressed in specific tumours." (PMID 34445211, 2021). "One of the substrates of PIM3 is the tumor suppresser gene pro-apoptotic BCL2 family member BAD." (PMID 26039373, 2015). "Interestingly, the proportion of mitotic cells was clearly higher in the Pim-3-overexpressing tumor tissues than in the controls." (PMID 26075720, 2015). "Comparison of phospho-CXCR4 signals to the average CXCR4 signals in each tumor revealed that both Pim-1 and Pim-3 had significantly increased the relative amounts of phospho-CXCR4, while Pim inhibition by DHPCC-9 had decreased it even below the level observed in the mock-transfected samples." (PMID 26075720, 2015). "Moreover, Pim-3 regulates tumor cell proliferation, survival, and apoptosis during early carcinogenesis." (PMID 25971209, 2015). "PIM3 has been shown to promote tumor cell growth through modulating cell cycle regulators." (PMID 22558405, 2012).